IL18 (interleukin 18)
Diseases named in the same sentence as IL18 in open-access papers (continued):
Sharing a sentence is not in itself a finding about the gene and the disease.
liver cirrhosis (14 papers, 2008 to 2026). "In conclusion, CD8+ and, to a lesser extent, CD4+ T cells from patients with compensated liver cirrhosis show suppressed responsiveness to stimulation with IL-12 + IL-18 compared with healthy individuals." (PMID 41028194, 2025). "Our systematic review and meta-analysis suggest that IL-10 -1082G/A, IL-18 -137G/C, TGF-β1 -509T/C and IFN-γ +874T/A are potentially associated with the risk of liver cirrhosis susceptibility." (PMID 37101651, 2023). "Discussion: This study suggests that IL-10 -1082G/A, IL-18 -137G/C, TGF-β1 -509T/C, and IFN-γ +874T/A were potentially associated with the risk of liver cirrhosis susceptibility." (PMID 37101651, 2023). "We found that IL-10 (−1082 GA + AA and AA), IL-18 (−137 GG), TGF-β1 (−509 T) and IFN-γ (+874 T) were potentially associated with the risk of liver cirrhosis susceptibility." (PMID 37101651, 2023). "The circulating levels of GSDMD and IL-18 are significantly upregulated in patients with liver cirrhosis and are correlated with disease severity." (PMID 38002346, 2023). "IL-18 was also up-regulated in serum from non JTT treated patients with liver cirrhosis, but to a lesser extent than in subjects treated with JTT." (PMID 19325795, 2008). "The patient showed clinical features associated with hyperkeratosis, liver cirrhosis and increased serum IL-18 but not of IL-1β." (PMID 38907167, 2024). "Gene polymorphisms of IL-10, IL-18, TGF-β1 have been confirmed to be related to liver cirrhosis by our study, however, it is accepted that IL-1β, IL-28, especially TNF-α plays an important role in the occurrence and development of liver cirrhosis." (PMID 37101651, 2023). "Gene polymorphisms of IL-10–1082 GA + AA vs. GG (OR = 1.43, 95% CI = 1.12–1.83), IL-10–1082 AA vs. GG (OR = 2.03, 95% CI = 1.36–3.02), IL-18 -137 GG vs. CC (OR = 3.84, 95% CI = 1.29–11.40), and TGF-β1 -509 T vs. C (OR = 2.52, 95% CI = 1.42–4.48) were significantly associated with liver cirrhosis." (PMID 37101651, 2023). "In addition, the phenotype of CD4+ and CD8+ T cells shifted towards activated and exhausted effector-memory and terminally differentiated cells in patients with compensated liver cirrhosis, which was parallelled by an impaired functional response upon stimulation with IL-12 + IL-18." (PMID 41028194, 2025). "Therefore, we analyzed the expression of pro-inflammatory and cytotoxic molecules in patients with compensated and decompensated liver cirrhosis compared with healthy controls in unstimulated conditions as well as after 24 h-stimulation with the third-signal cytokines IL-12 + IL-18." (PMID 41028194, 2025). "For instance, IL-18 was found to be significantly expressed in LGHDS and LDSDS in patients with liver cirrhosis, by statistics analysis." (PMID 31768187, 2019). "Furthermore, following stimulation with IL-12 + IL-18, the expression of IFNγ and TNFα was reduced in CD8+ T cells from compensated liver cirrhosis in comparison with healthy controls." (PMID 41028194, 2025). "We found that IL-15 expression was significantly higher in the hepatic mononuclear cells from participants with NASH or liver cirrhosis than in those from controls, but IL18 expression did not significantly differ among the three groups." (PMID 37735474, 2023).
renal failure (14 papers, 2008 to 2024). "We also identified several organ-failure-specific immunological markers, including those for respiratory (IL-18, IL-15, Gal-9) or kidney failure (CD28, VEGF)." (PMID 34177897, 2021). "This study investigated whether Il18−/− mice develop kidney failure as they age and whether IL-18 has beneficial or damaging effects on the kidney." (PMID 29514661, 2018). "The strongest and most significant differences have been found for albumin, 3-NT, IL-18, AOPP, NT-proBNP, and phosphates, which may suggest the importance of kidney failure-associated factors such us inflammation, malnutrition, and nitrosative and oxidative stress." (PMID 35204237, 2022).
co-infection (13 papers, 2011 to 2025). "In VL/HIV co-infection, the immune response is predominantly of the Th2 type, characterized by reduced levels of IL-12, IL-18, and IFN-γ." (PMID 39186781, 2024). "In this study, we additionally report the regulation of proinflammatory (IL1-α, IL1-β, IL6, IL8, IL18, and TNF-α) and regulatory (IL10, IL22, IL23, and IL33) cytokines associated with single-PDCoV and -PEDV infection, as well as PDCoV/PEDV co-infection." (PMID 36376395, 2022). "It is known that levels of inflammatory mediators such as IL-6 and IL-18 were higher in the patients with co-infection of influenza virus and bacteria than in patients with bacterial pneumonia or influenza virus infection alone." (PMID 30551738, 2018). "The antigen-independent responsiveness of exhausted CD8 T cells was also investigated following co-infection with Listeria monocytogenes, which induces the expression of IL-12 and IL-18." (PMID 21980291, 2011). "We also show that whereas conventional anti-viral CD8 T cells can sense a bacterial co-infection that induces IL-12 and IL-18 production, the exhausted cells fail to respond." (PMID 21980291, 2011). "Thus, it looked like NLRP6 and IL-18 could be promising molecules to target early on in this coinfection to stop an overactive inflammatory response and to stop damage to the tissues." (PMID 36556283, 2022). "In this way, Mtb-induced production of IL-18, protective for Mtb infection, appeared to be detrimental for HIV-1/TB coinfection, contributing to HIV-1 persistence and tissue damage." (PMID 37376629, 2023). "Our findings suggest that the cytokines TNF-α, IL-1β, and IFN-γ are central to the immune response in HIV-CC co-infection whereas others like IL-18 are not." (PMID 40046043, 2025). "In clinical falciparum malaria, with and without HIV co-infection, data on IL-18 and in particular on its binding protein, IL-18bp, is scarce." (PMID 34663245, 2021). "In the present study we examined plasma levels of IL-18 and IL-18bp in a cohort of non-pregnant adult patients with falciparum malaria with and without HIV co-infection, arriving at the Central Hospital of Maputo, Mozambique." (PMID 34663245, 2021). "Interestingly, non-HIV patients with co-infection and pneumocystosis alone showed lower levels of SP-A, IL-1β, TNF-α, IFN-γ, IL-18, IL-17A, and IL-23 than histoplasmosis patients, suggesting an immunomodulatory ability of P. jirovecii over H. capsulatum response." (PMID 34829225, 2021).
E. coli infection (13 papers, 2017 to 2023). "Our findings are in agreement with these observations: the reduction in mtDNA caused by NAC, BAPTA-AM, or 2-APB during E. coli infection also reduced the expression of inflammatory factors IL-1β and IL-18." (PMID 36430657, 2022). "There was a dramatic up-regulation in the level of Il-18 expression in cells with E. coli infection alone, at different time points tested (3, 6, and 9 h), when compared with that in untreated control PMECs (p = 0.004, p < 0.001, and p < 0.001, respectively)." (PMID 32823867, 2020). "Up-regulation of interleukin (Il)-1β, Il-6, Il-8, Il-18, tumor necrosis factor alpha, and chemokine Cxcl2 expression after E. coli infection was attenuated by L. johnsonii L531." (PMID 32823867, 2020). "L. rhamnosus GR-1 inhibits activation of ASC-dependent NLRP3 and NLRC4 inflammasome activation and production of the downstream proinflammatory cytokines IL-lβ and IL-18 during E. coli infection." (PMID 30087667, 2018). "During E. coli infection in the present study, L. rhamnosus GR-1 decreased the secretion of IL-lβ and IL-18, in part due to suppression of ASC-dependent NLRC4 inflammasome activation." (PMID 30087667, 2018). "Our findings indicate that E. coli infection activates caspase-4, subsequently resulting in cell pyroptosis and maturation of IL-1β and IL-18 via an NLRP3 inflammasome-dependent and ASC-independent pathway." (PMID 30087667, 2018). "We provide evidence that L. rhamnosus GR-1 suppresses E. coli-induced ASC-dependent activation of NLRP3 and NLRC4 inflammasomes and thus decreases production of IL-lβ and IL-18 during E. coli infection." (PMID 30087667, 2018). "Our data indicate that L. rhamnosus GR-1 suppresses activation of ASC-dependent NLRP3 and NLRC4 inflammasomes and production of downstream IL-lβ and IL-18 during E. coli infection." (PMID 30087667, 2018). "Third, both IL-1β and IL-18 secretion in response to E. coli infections was dramatically diminished in GBPchr3−/− BMDMs." (PMID 28974614, 2017). "In this study, we observed that Ybt promotes chromosome aggregation in intestinal epithelial cells caused by E. coli infection, resulting in a large number of cells being TUNEL positive, and a substantial increase in inflammatory IL-1β and IL-18 in intestinal epithelial cells." (PMID 37511208, 2023). "Furthermore, E. coli infection also resulted in a significant up-regulation in the protein levels of IL-1β and IL-18, while these effects were attenuated by Z. morio hemolymph or gentamicin administration." (PMID 36362066, 2022). "Moreover, Ager−/− BMDM was also resistant to LPS electroporation or E. coli infection-induced cytotoxicity, IL-1β release, and IL-18 release in LPS-primed BMDMs." (PMID 31440260, 2019). "ASC knockout diminished, but did not completely prevent, increased production of IL-1β and IL-18 and cell pyroptosis associated with E. coli infection, whereas pre-incubation with L. rhamnosus GR-1 inhibited this increase." (PMID 30087667, 2018). "In this study, we demonstrated the role of duNLRP3 in the expression of inflammatory cytokines IL-1β, IL-18, and TNF-α mRNA after E. coli infection." (PMID 30349536, 2018). "The results show that IL-1β, IL-18, and TNF-α in the liver, spleen, and brain of the NLRP3-lentiviral vector-injected group mostly increased after E. coli infection." (PMID 30349536, 2018). "The knockdown of duNLRP3 significantly impaired the mRNA expression levels of IL-1β, IL-18, and TNF-α induced by E. coli infection (P < 0.01)." (PMID 30349536, 2018). "We also detected the mRNA expression levels of inflammatory cytokines IL-1β, IL-18, and TNF-α in the liver, spleen, and brain after the E. coli infection." (PMID 30349536, 2018). "We found that GBP2−/− BMDMs mimicked GBPchr3−/− BMDMs in their unresponsiveness to E. coli infections, as measured by LDH release as a marker of cell death and secretion of IL-1β and IL-18." (PMID 28974614, 2017).
E. coli infection (continued). "Our study demonstrated that Ybt-induced E. coli infection led to intestinal epithelial cell pyroptosis via the NLRP3 pathway, resulting in the release of large amounts of IL-1β and IL-18, which promoted gut inflammation and contributed to E. coli-induced intestinal damage." (PMID 37511208, 2023). "It must be noted that ASC deficiency reduced, but did not abolish, caspase-1 processing, IL-1β and IL-18 maturation, and cell pyroptosis during E. coli infection." (PMID 30087667, 2018). "All these results suggest that duNLRP3 could induce the mRNA expression of IL-1β, IL-18, and TNF-α during E. coli infection, shows that duNLRP3 plays an important regulatory role in the innate immune response to E. coli." (PMID 30349536, 2018). "In addition, the mRNA expression levels of IL-1β, IL-18, and TNF-α induced by E. coli infection were significantly up-regulated in comparison with the NC-lentiviral vector group (P < 0.01)." (PMID 30349536, 2018). "We hypothesized that during E. coli infection, the activity of NLRP3 and NLRC4 inflammasomes is differentially regulated by L. rhamnosus GR-1, inducing maturation of IL-1β and IL-18 or cell pyroptosis, depending on ASC." (PMID 30087667, 2018).
epilepsy (13 papers, 2019 to 2025). A brain disorder characterized by episodes of abnormally increased neuronal discharge resulting in transient episodes of sensory or motor neurological dysfunction, or psychic dysfunction. "It has been suggested that the pro‐inflammatory effects of IL‐18 contribute to the development and progression of epilepsy, as well as the associated structural damage." (PMID 39888294, 2025). "In the MR analysis of the present study, IL-18 was confirmed to cause epilepsy development only with the MR approach, which was less effective than the IVW approach." (PMID 37470000, 2023). "Clinical studies have found that the expression levels of IL‐1β,20 IL‐6,21 IL‐18,20, 22 and IL‐33 23 in the serum of epilepsy patients are elevated." (PMID 40103702, 2025). "VX-765 reduces disease severity and the expression of IL-1β and IL-18 in animal models of RA, skin inflammation, and epilepsy." (PMID 35628185, 2022). "Recently, the NLRP3 inflammasome, a key constituent of the inflammasome complex, has been implicated in the sterile inflammatory response via the processing of caspase-1, IL-18, and IL-1β in the setting of epilepsy and some other neurological diseases." (PMID 32005256, 2020). "Epilepsy patients had significantly higher serum levels of IL‐18." (PMID 40103702, 2025). "Moreover, NF-κB (P65) signaling would be activated, leading to the upregulated transcription of inflammasome-related components, such as NLRP3, pro-IL-1, and pro-IL-18 in epilepsy." (PMID 37367679, 2023). "IL-18 gene amplification and elevated IL-18 concentrations have been observed in patients with temporal lobe epilepsy, suggesting that a genotype can increase inflammatory factors, leading to epilepsy." (PMID 37470000, 2023). "Proinflammatory cytokines (IL-1β, IL-6, and IL-18) contribute to the pathophysiology of epilepsy through several pathways: modulating glutamatergic transmission, enhancing N-methyl-D-aspartate receptor function by activation of SRC tyrosine kinase, and altering GABAergic neurotransmission." (PMID 35624482, 2022). "Moreover, the expression of several cytokines downstream of P2X7R activation (e.g., IL-1β, IL-18) has been found altered in the blood of patients with epilepsy." (PMID 34572093, 2021). "Finally, similar to KC/GRO levels, no changes were observed between conditions (control vs. status epilepticus/epilepsy) in plasma concentrations for IL-1β, IL-6, or IL-18 in wt mice." (PMID 34572093, 2021). "Laboratory studies from epilepsy have shown that the levels of inflammasomes (NLRP1, NLRP3, caspase 1, IL-1β, ASC, AIM2, gasdermin D, IL-18, intracellular calcium ion, sTNFr2) were also elevated." (PMID 40217546, 2025). "In a mouse model of pilocarpine-induced epilepsy, four studies consistently show that inflammation is enhanced through NLRP3, caspase 1, ASC, gasdermin D, IL-1β, and IL-18 pathways." (PMID 40217546, 2025). "Other Ct/Cm concentrations were significantly higher in MUE cases (IL‐8: median 101 pg/mL, range 144, p = 0.019; IL‐18: median 3 pg/mL, range 0.52, p < 0.001; MCP‐1: median 814 pg/mL, range 1319, p = 0.004; and IL‐6: median 5 pg/mL, range 16, p < 0.001) compared to epilepsy and neoplasia." (PMID 40859633, 2025). "Since IL-1β and IL-18 are signaling pathways downstream of NLRP3, our data can indirectly prove that GPR120, as a ligand of NLRP3, regulates the activation of NLRP3 and induces neuroinflammation in epilepsy." (PMID 35624482, 2022). "Therefore, we used the cytokines IL-1β, IL-18, and IL-6, which are all commonly found in neuroinflammation as inflammatory markers to explore the effect of treatment with GPR120-AAV-KD and GPR120-AAV-OE on neuroinflammation in epilepsy." (PMID 35624482, 2022). "Finally, no significant changes in IL-18 plasma levels were observed following status epilepticus or during epilepsy between genotypes." (PMID 34572093, 2021).
glaucoma (13 papers, 2008 to 2025). Increased pressure in the eyeball due to obstruction of the outflow of aqueous humor. "Inflammatory factors, such as TNF, IL-1β, IL-18 and MMP, can promote the death of RGCs, which is a hallmark of glaucoma development." (PMID 38437213, 2024). "NFKB1, TLR9, and HDAC4 were predicted to be upregulated in glaucoma and their mRNA level increased according to the RT-qPCR data, meanwhile, IL18 was predicted to be downregulated in glaucoma and its mRNA level was also increased according to RT-qPCR." (PMID 37605653, 2023). "IL18 has been implicated in several ocular diseases, including AMD, retinopathy of prematurity, and glaucoma." (PMID 35203520, 2022). "Tumor-necrosis-factor-alpha (TNFα) and interleukin-18 (IL-18) levels in AH were different between all three groups (glaucoma>POH>normal) (p = .05, p = .02, respectively)." (PMID 35998207, 2022). "We then examined the gene expression of several proinflammatory cytokines (TNFα, IL-1β, IL-6, and IL-18) and chemokines (MIP-1α, MIP-1β, MIP-2, MCPI, and IP10) that have been implicated in human and experimental models of glaucoma." (PMID 31570110, 2019). "The results suggest that IL-18 and PDGF-BB may be upstream causes of AMD; Genetically predicted RANTES had protective effect on glaucoma; IL-10 had protective effect on DR." (PMID 40687727, 2025). "This study identified IL18, TLR9, NFKB1, HDAC4, FKBP2, and KITLG as hub genes in glaucoma that are gut microbiota-related as well as showed that the regulation of immune response by gut microbiota is associated with glaucoma." (PMID 37605653, 2023). "Additionally, dogs with glaucoma had higher levels of IL-18 and TNFα in AH compared to dogs with anterior uveitis and POH following phacoemulsification." (PMID 35998207, 2022). "Interestingly, AH levels of IL-18 and TNFα were higher in glaucoma eyes than POH eyes following phacoemulsification surgery." (PMID 35998207, 2022). "IL-1 family members have been shown to play a role in glaucoma pathogenesis, with IL-18 expression increasing with age in the ciliary body, iris and aqueous humor of DBA/2J mice, a model of pigmentary glaucoma that naturally presents with increased IOP, RGC loss, and pigmentary dispersion." (PMID 31379825, 2019). "Additionally, IL-18 and TNFα were higher in patients with glaucoma compared to the ‘POH group’." (PMID 35998207, 2022). "TNFα and IL-18 levels in AH were different among all three groups with the ‘glaucoma group’ having the highest levels followed by the ‘POH group’ and ‘normal group’ (TNFα p = .05 and IL-18 p = .02)." (PMID 35998207, 2022). "Clear trends exist between the role of IL-1β as a regulator of cytokine production and cell death across many retinal diseases including AMD, DR, RP, glaucoma and ROP, and IL-18, which modulates neovascular aspects of these diseases." (PMID 31379825, 2019). "An increase in IL18 was also observed in an induced ocular hypertension model as well as in high-pressure DBA2/J mice, suggesting a role of this interleukin in glaucoma pathogenesis." (PMID 36291747, 2022). "By further selecting five natural active ingredients with anti-inflammatory and eye-protective effects (anthocyanin, procyanidin, lutein, quercetin, resveratrol) for molecular docking with IL-18 and RANTES, the results showed that anthocyanin may have a good therapeutic effect on glaucoma." (PMID 40687727, 2025). "This may account for the higher pro-inflammatory cytokine values in the the ‘glaucoma group’ compared to the ‘POH group’, suggesting that IL-18 may be associated with increased IOP rather than anterior uveitis and POH." (PMID 35998207, 2022).